FAP (fibroblast activation protein alpha)
Diseases named in the same sentence as FAP in open-access papers (continued):
Sharing a sentence is not in itself a finding about the gene and the disease.
gliosarcoma (2 papers, 2010 to 2020). A rare histological variant of glioblastoma (WHO grade IV) characterized by a biphasic tissue pattern with alternating areas displaying glial and mesenchymal differentiation (WHO). "Furthermore, our data suggest that FAP is particularly prevalent in the gliosarcoma variant and is relatively stable between primary and recurrent tumors." (PMID 33082953, 2020). "Immunostaining of tissue sections revealed that, although most patient specimens expressed some level of FAP on the tumor cells, the intensity of expression and the proportion of cells positive varied widely, with particularly strong expression noted on the gliosarcoma variant." (PMID 33082953, 2020). "In gliosarcoma, FAP expression was limited to the mesenchymal/sarcomatous areas of these biphasic tumors, being absent from the glial areas." (PMID 33082953, 2020). "Within gliosarcomas, FAP staining was virtually uniform in the portion of the tumor showing sarcomatous, spindle morphology (mesenchymal‐like) but absent from the glial cell compartment." (PMID 33082953, 2020). "Of interest, four cases of the gliosarcoma variant were included in our analysis, and all of these had particularly strong expression of FAP (P < 0.005 compared to nongliosarcoma tumors)." (PMID 33082953, 2020).
IgG4 related disease (2 papers, 2021 to 2025). "However, one key disadvantage, regarding the limited specificity of FAPI-uptake needs to be acknowledged: FAP is overexpressed on cancer-associated fibroblasts, but also on activated fibroblasts in inflammatory disease, such as IgG4 related disease." (PMID 40022163, 2025). "FAP-specific PET has been used in cardiac imaging, IgG4-related disease, benign tumors as well as various kinds of inflammation." (PMID 33606104, 2021).
inflammatory bowel disease (2 papers, 2018 to 2024). A spectrum of small and large bowel inflammatory diseases of unknown etiology. "However, it has been studied in various other conditions, notably in patients with cancer, inflammatory bowel disease or acute heart failure, who also exhibited a lower plasmatic FAP concentration compared with healthy volunteers, despite an overexpression of FAP in diseased tissues." (PMID 39188902, 2024). "Conditions diagnosed prior to endoscopy for H. pylori in this group included celiac disease, inflammatory bowel disease (IBD), and positive FAP gene." (PMID 29805445, 2018).
influenza (2 papers, 2017). An acute viral infection of the respiratory tract, occurring in isolated cases, in epidemics, or in pandemics; it is caused by serologically different strains of viruses (influenzaviruses) designated A, B, and C, has a 3-day incubation period, and usually lasts for 3 to 10 days. "We used an adoptive transfer model to characterise the effect of FAP deficiency on antigen-specific anti-influenza T cell responses." (PMID 28158223, 2017). "Nonetheless, FAP deficient mice showed similar pathologic kinetics to wildtype controls, and were capable of supporting normal anti-influenza T and B cell responses." (PMID 28158223, 2017). "We conclude that deficiency of FAP does not compromise the T and B cell responses in acute influenza infection in vivo." (PMID 28158223, 2017). "Finally, the role of FAP in anti-influenza antibody production was examined in mice infected with 50 pfu and 25 pfu influenza PR/8 virus." (PMID 28158223, 2017). "FAP appears to be dispensable in anti-influenza adaptive immunity." (PMID 28158223, 2017). "Secondary sublethal infection with a heterologous strain of influenza also did not exacerbate weight loss response in FAP knockout mice when compared to wildtype (data not shown)." (PMID 28158223, 2017). "However, in our model of intranasal influenza infection, FAP deficiency did not affect viral clearance in the lung and did not worsen the immunopathological response to infection as assessed by the combined parameters of weight loss, T cell and B cell functions." (PMID 28158223, 2017). "We showed that although the expression of FAP is increased in the lungs and lung-draining lymph nodes in influenza infection, its absence did not alter the antiviral CD8+ T cell and B cell responses, nor affected the course of recovery in infected mice." (PMID 28158223, 2017). "Together, these observations indicate that the absence of FAP did not impair the anti-influenza response." (PMID 28158223, 2017). "While our data supports the notion that ablation of FAP activity does not adversely affect the anti-influenza response, it does not contradict earlier reports of a requirement for FAP+ cells in regulating the number of naive T cells in the lymph node via chemokine production." (PMID 28158223, 2017). "Our recent data indicates that lacking FAP does not alter immunity to influenza in mice." (PMID 28582421, 2017). "Our results suggest that FAP activity is not required for anti-influenza adaptive immunity." (PMID 28158223, 2017).
Insulin resistance (2 papers, 2020 to 2025). Increased resistance towards insulin, that is, diminished effectiveness of insulin in reducing blood glucose levels. "Recently, FAP-deficient mice have been reported to exhibit improved insulin resistance, glucose tolerance, and liver steatosis." (PMID 33277568, 2020). "Emerging evidence suggests FAP may synergistically interact with diabetic metabolic derangements (hyperglycemia and insulin resistance) to exacerbate myocardial stiffness, which is a hallmark of HFpEF." (PMID 40855978, 2025). "Correspondingly, FAP knockout mice fed with a high-fat diet improved insulin resistance and glucose tolerance in the liver and adipose tissue, similar to those observed in the FGF21 transgenic mice." (PMID 33277568, 2020). "In support of this approach, an FAP knockout mouse prevented liver steatosis, insulin resistance, glucose tolerance, and increased FGF21 in diet-induced obese mice." (PMID 33277568, 2020). "Additionally, administration of a known FAP inhibitor (Talabostat, TB) to diet-induced obese mice improved insulin resistance and increased endogenous intact FGF21 level." (PMID 33277568, 2020).
invasive carcinoma (2 papers, 2023). A carcinoma that is not confined to the epithelium, and has spread to the surrounding stroma. "In contrast, primary invasive carcinomas and distant metastases contain a unique population of cells that coexpress pan-CK and FAP, indicating a hybrid phenotype." (PMID 37607007, 2023).
ischemic stroke (2 papers, 2020 to 2022). A stroke disorder caused by obstruction of blood flow to the brain, due to thrombotic (local blood clot formation) or embolic (due to a blood clot or other material traveling from another site) event. "Therefore, FAP might enable individualized risk stratification in ischemic stroke." (PMID 36568546, 2022).
kidney cancer (2 papers, 2023 to 2024). Primary or metastatic malignant neoplasm involving the kidney. "In the literature, FAP is expressed by kidney cancer stromal fibroblasts and is associated with tumor aggressiveness." (PMID 36975533, 2023). "At low FAP expressions (for instance, kidney cancer), the simulated FAP expression distribution appears multimodal (with modes representing the zero, low, medium and high FAP expression)." (PMID 39444607, 2024).
large cell neuroendocrine carcinoma (2 papers, 2024 to 2025). A usually aggressive carcinoma composed of large malignant cells which display neuroendocrine characteristics. "NSCLC can express FAP in up to 100% of cases, whereas small-cell lung cancer (SCLC) and large-cell neuroendocrine carcinoma (LCNC) exhibit FAP expression in up to 67% of cases." (PMID 40283957, 2025).
leukemia (2 papers, 2022 to 2023). A malignant (clonal) hematologic disorder, involving hematopoietic stem cells and characterized by the presence of primitive or atypical myeloid or lymphoid cells in the bone marrow and the blood. "Although FAP and PDGFRβ expression was strongly diminished in LYNKO BMSC and both molecules were associated with the leukemia protective function of stromal cells, both FAP- and PDGFRβ-knockdown did not impair stromal feeding capacity in CLL co-culture." (PMID 36899005, 2023).
myocarditis (2 papers, 2022 to 2026). Myocarditis is a condition that is characterized by inflammation of the heart muscle (myocardium). "To facilitate the clinical translation of FAP.CAR-T cells in treatment of myocarditis, we constructed a CAR molecule targeting human FAP based on MO36 mAb clone by fusing its scFv fragment with human CD28 and CD3z endodomain (referred as hFAP.CAR)." (PMID 41356193, 2026). "While FAP.CAR-T therapy demonstrated a favorable safety profile in our chronic myocarditis models, the physiological role of FAP+ fibroblasts warrants careful consideration." (PMID 41356193, 2026). "Another potential marker of early stages of ICI myocarditis is fibroblast activating protein (FAP), which is a protein that gets significantly upregulated in cancer tissue, atherosclerosis, arthritis and fibrosis." (PMID 35369354, 2022). "Additionally, histological quantitative analysis of 30 additional myocarditis cases confirmed that FAP+ areas were significantly correlated with fibrosis severity (r2 = 0.904, P < 0.0001)." (PMID 41356193, 2026). "Here, we address these gaps by testing FAP.CAR-T cells in autoimmune (EAM) and viral (CVB3) myocarditis models, which recapitulate chronic inflammation and fibrosis that are commonly observed in patients with chronic myocarditis." (PMID 41356193, 2026). "We engineered FAP-targeted CAR-T (FAP.CAR-T) cells and tested their efficacy in autoimmune (EAM) and viral (CVB3) myocarditis models." (PMID 41356193, 2026). "Fibroblast-specific genes were upregulated in both myocarditis and DCM versus controls, with FAP showing the largest fold change." (PMID 41356193, 2026).
myxoma (2 papers, 2024). A benign soft tissue neoplasm characterized by the presence of spindle and stellate cells, lobulated growth pattern, and myxoid stroma formation. "Fibroblasts within myxomas exhibit an activated state, characterized by elevated expression of well-known activated fibroblast markers 18such as POSTN, NOX4, FAP, and COL1A2." (PMID 39090109, 2024). "In contrast, radiolabeled FAPα inhibitors may offer visualization for non-skeletal lesions in FD/MAS, i.e., intramuscular myxomas, or others that remain to be characterized." (PMID 39273006, 2024).
pleural mesothelioma (2 papers, 2023 to 2025). A neoplasm that arises from the mesothelial cells of the pleura. "first used FAP CAR-T cell therapy to eliminate FAP+ tumor cells in pleural mesothelioma (MPM) and achieved therapeutic effects in vivo and in vitro." (PMID 40607439, 2025). "Hence, they propose that FAP is not a good marker to characterize CAFs in Pleural mesotheliomas." (PMID 38192631, 2023).
pneumonia (2 papers, 2023 to 2024). An acute, acute and chronic, or chronic inflammation focally or diffusely affecting the lung parenchyma, caused by an infection in one or both of the lungs (by bacteria, viruses, fungi, or mycoplasma.). "In this study, we assess the concordance of microbiological detections between oropharyngeal- (OP) and LRT samples from patients presenting to the ED with CAP using a syndromic PCR-based respiratory panel [Biofire FilmArray Pneumonia plus (FAP plus)]." (PMID 37585220, 2023). "However, strong FAP expression and high 68Ga-FAPI-04 uptake were also reported in benign conditions such as organising pneumonia, tuberculosis and cryptococcosis." (PMID 39598380, 2024).
prion disease (2 papers, 2018 to 2023). A transmissible disease that is caused by a protein that is able to induce abnormal folding of normal cellular proteins, leading to characteristic spongiform brain changes, which are associated with neuronal loss without an inflammatory response. "In addition, recent clinical studies have revealed the presence of systemic polyneuropathy associated with FAP mutations in patients with spinocerebral ataxia, amyotrophic lateral sclerosis, and new familial systematic prion disease." (PMID 29593496, 2018). "In contrast to HuDPP4, HuFAP efficiently cleaved HuPrP in cells, indicating that the S9B peptidase family is still connected to β-cleavage in humans; however, it remains to be seen whether FAP has any involvement in natural or iatrogenic prion diseases." (PMID 36574660, 2023). "In contrast to DPP4, FAP may act as a tissue-specific regulator of PrPC β-cleavage outside of a prion disease context, perhaps affecting the physiological function of PrPC." (PMID 36574660, 2023).
psoriasis (2 papers, 2021 to 2026). An autoimmune condition characterized by red, well-delineated plaques with silvery scales that are usually on the extensor surfaces and scalp. "Unfortunately, no data has been reported on FAP expression in dermal fibroblasts in, e.g., dermatitis or systemic auto immune diseases with skin involvement such as systemic lupus erythematosus, psoriasis or arthritis psoriatica to support this idea." (PMID 34884484, 2021).
scoliosis (2 papers, 2023 to 2025). A congenital or acquired spinal deformity characterized by lateral curvature of the spine. "Therefore, FAP is likely to affect scoliosis by affecting the endplate cartilage, and we prove that FAP was negatively correlated with the AIS degree for the first time." (PMID 37667193, 2023).
soft tissue tumor (2 papers, 2009 to 2023). "In this study, the expression of FAP by IHC and RNA sequencing was shown to be variable across the different bone and soft tissue tumor subtypes with the highest expression occurring in DF, MFS, SFT, and UPS samples." (PMID 37333052, 2023). "In the current study, the expression of FAP by IHC and RNA sequencing was shown to be variable across the different bone and soft tissue tumor subtypes with the highest expression occurring in DF, MFS, SFT, and UPS samples." (PMID 37333052, 2023). "The present study was designed to identify cell types that express FAP and DPP-IV in human bone and soft tissue tumours, and to determine whether there are any correlations between the expression of FAP and DPP-IV and the malignant potential of tumours." (PMID 19817894, 2009).
steatosis (2 papers, 2021 to 2025). Increased lipid within the cytoplasm of cells. "Five circulating proteins, including Cathepsin O (CTSO), Cadherin 2 (CDH2), and Prolyl endopeptidase (FAP), were identified as biomarkers for steatosis." (PMID 39017916, 2025). "Our results indicated that CTSO and FAP were affected not only by steatosis grade but also by the gender of the subject." (PMID 39017916, 2025). "The study identified five circulating proteins associated with the steatosis grade in the liver: Cathepsin O (CTSO), Cadherin 2 (CDH2), Leukocyte immunoglobulin-like receptor subfamily A member 5 (LILRA5), and Serpin B6 (SERPINB6); and Prolyl endopeptidase (FAP)." (PMID 39017916, 2025). "The candidates to be combined in future algorithms for steatosis are CTSO, CDH2, LILRA5, SERPINB6, and FAP." (PMID 39017916, 2025).
systemic sclerosis (2 papers, 2021 to 2023). A chronic disorder, possibly autoimmune, marked by excessive production of collagen which results in hardening and thickening of body tissues. "Targeted photodynamic therapy with an anti-FAP photosensitizer exhibits a dose-dependent therapeutic effect on skin fibroblasts of patients with systemic sclerosis." (PMID 37033989, 2023). "On the other hand, FAP-inhibiting radiopharmaceuticals have shown theranostic promise in various malignancies and other disorders characterized by tissue fibrosis, such as systemic sclerosis, rheumatoid arthritis, and IgG4-related disease." (PMID 37033989, 2023). "In addition, FAP-specific PET might be used to monitor other diseases that are primarily characterized by inflammation and/or fibrotic remodelling such as systemic sclerosis and vasculitis." (PMID 33606104, 2021).
Thrombocytopenia (2 papers, 2022 to 2026). A reduction in the number of circulating thrombocytes. "FAP-targeted RLT with 90Y-FAPI-46 was well tolerated, with a low rate of attributable adverse events, including thrombocytopenia." (PMID 34385340, 2022).
ulcer (2 papers, 2021 to 2022). "In situ localization of inflammatory fibroblasts by PDPN and FAP revealed their proximity to neutrophils in ulcers." (PMID 34675383, 2021). "We stained for inflammatory fibroblast markers, CHI3L1 and TIMP1, together with pan-fibroblast marker fibroblast activation protein (FAP) and discovered elevated numbers of triple-positive cells within the ulcer area of healing DFUs, with the cells forming dense aggregates." (PMID 35013299, 2022).
urothelial carcinoma (2 papers, 2022 to 2023). A malignant neoplasm derived from the transitional epithelium of the urinary tract (urinary bladder, ureter, urethra, or renal pelvis). "In urothelial carcinoma, FAP expression was demonstrated to correlate with tumor aggressivity." (PMID 37111363, 2023).
uterine corpus endometrial carcinoma (2 papers, 2023 to 2024). A endometrial carcinoma (disease) that involves the body of uterus. "However, in Uterine corpus endometrial carcinoma (UCEC) and Uterine carcinosarcoma (UCS), FAP expression was reduced." (PMID 39055892, 2024).
vasculitis (2 papers, 2017 to 2021). "Because the physiological role of FAP in vasculitis (including KD) is unknown, a detailed analysis of this protein’s functions should also be performed." (PMID 28900133, 2017).
viral infection (2 papers, 2023 to 2024). "Experimental depletion of FAP+ cells decreased TLS formation during viral infection directly demonstrating their importance." (PMID 37520560, 2023).
abdominal aortic aneurysm (1 paper, 2025). Enlargement and ballooning of the vessel that supplies arterial blood to the abdomen, pelvis and legs. "This study investigates the molecular mechanisms of fibroblast activation protein (FAP) in vascular smooth muscle cells (VSMCs) during abdominal aortic aneurysm (AAA) development." (PMID 40520892, 2025).
Acute hepatitis (1 paper, 2025). Acute hepatic injury resulting from inflammation typically accompanied by increased serum alanine transaminase activity. "Acute hepatitis causes hepatic stellate cells to differentiate into myofibroblasts expressing FAP on their surface, a finding confirmed through Western blot experiments." (PMID 39861738, 2025).
adrenal tumors (1 paper, 2022). "For example, the association between FAP and adrenal tumors provided the basis for the insights into the role of β-catenin signaling in adrenal tumors, while the link between ACC and BWS combined with gene expression profiling suggested the IGF-1 receptor as a target for ACC therapy." (PMID 36105398, 2022).
age (1 paper, 2025). A temporal measurement of the time period elapsed since an identifiable point in the life cycle of an organism. "Given these roles, FAP‐expressing activated fibroblasts may play a significant role in age related muscle degeneration and fat infiltration." (PMID 39956945, 2025).
alcohol abuse (1 paper, 2024). The use of alcoholic beverages to excess, either on individual occasions ("binge drinking") or as a regular practice. "Expression of FAP, α-SMA, PDGFRb or periostin was independent from nicotine or alcohol abuse, UICC stage, sex or HPV status." (PMID 38328551, 2024).
anal carcinoma (1 paper, 2020). "Especially anal cancer, an entity where radiotherapy is a mainstay of definitive treatment, showed high uptake with FAP-specific PET." (PMID 32942573, 2020).